REST (RE1 silencing transcription factor)
Diseases named in the same sentence as REST in open-access papers (continued):
Sharing a sentence is not in itself a finding about the gene and the disease.
fibroid (continued). "We observed that upon siRNA-mediated knockdown of PRICKLE1 in cultured primary MSMCs, REST expression was correspondingly reduced, indicating that the low PRICKLE1 levels in leiomyomas may indeed trigger the decline in REST stability and function." (PMID 39314474, 2024). "In contrast to this hypothesis, our results indicated that EZH2 expression is significantly upregulated in leiomyoma samples both at mRNA and protein levels and this upregulation was inversely correlated with the expression of PRICKLE1 and REST." (PMID 39314474, 2024). "Conversely, overexpression of Flag-tagged PRICKLE1 in cultured primary LSMCs led to a matching restoration of REST expression without altering REST mRNA expression, confirming that the loss of PRICKLE1 expression in leiomyoma is linked to the destabilization of REST." (PMID 39314474, 2024). "The absence of functional REST results in aberrant GPR10 expression, which promotes fibroid cell proliferation and contributes to the pathogenesis of leiomyomas." (PMID 41601477, 2026).
migraine (4 papers, 2019 to 2024). "In summary, analyses presented in this paper validate polymorphisms in p31.1 region of chromosome 1, PRDM16, ADGRL2, REST and HPSE2 genes in migraine." (PMID 34972135, 2021). "However, REST was not identified in the top 5 migraine-relevant tissues." (PMID 37245199, 2023).
neural tumors (4 papers, 2018 to 2025). "A decreased expression of REST is observed in non-neural tumors and acts as a tumor-suppressor, whereas an increased level of REST expression is observed in neural tumors and acts as a tumor promoter." (PMID 40006989, 2025). "Taken together, these findings highlight REST as a potential therapeutic target for nervous system cancers, offering opportunities for developing novel treatment approaches aimed at disrupting REST-mediated tumorigenic processes." (PMID 37892159, 2023). "The dysregulation of REST was found in various nervous system cancers, often playing promoting roles." (PMID 37892159, 2023). "REST also acts as an oncogene and promotes cell proliferation in neural tumors." (PMID 40006989, 2025). "Dysregulation of REST was also found in nervous and non-nervous system cancers." (PMID 37892159, 2023). "Unlike in nervous system cancers, the loss of REST repression occurs in most non-nervous system cancers." (PMID 37892159, 2023).
pancreatic cancer (4 papers, 2019 to 2025). "Gene expression profiling from independent Gene Expression Omnibus (GEO) datasets confirms that REST mRNA levels are elevated in human pancreatic tumor samples and correspond with lower levels of REST target genes such as SNAP25, CHGA, and PDGB5." (PMID 32080178, 2020). "This specific isoform of REST holds promising potential to serve as a specific prognostic biomarker and a sensitive therapy target for pancreatic cancer." (PMID 31041193, 2019). "Further in vitro and in vivo functional experiments showed that knockdown of REST suppressed growth and metastasis of pancreatic cancer cell lines and xenograft tumors." (PMID 31041193, 2019). "To investigate the potential role of REST in the metastasis of pancreatic cancer, we knocked down the expression of REST in PANC-1 and AsPC-1 cell lines." (PMID 31041193, 2019). "These in vitro and in vivo results suggested that REST may function as a key promoter for pancreatic cancer metastasis." (PMID 31041193, 2019). "In conclusion, our results of bioinformatic analysis, in vitro and in vivo functional analysis suggested that REST may serve as a promoter of metastasis in pancreatic cancer." (PMID 31041193, 2019). "Future directions could investigate REST in maintaining acinar cell organization during KRAS-driven ADM, which is believed to be an initial event towards pancreatic cancer development." (PMID 32080178, 2020). "Finally, we investigated the potential correlation of REST with MAPK and Wnt/beta-catenin signaling pathway in pancreatic cancer." (PMID 31041193, 2019). "However, studies on the role of REST in pancreatic cancer progression has not been reported." (PMID 31041193, 2019).
status epilepticus (4 papers, 2015 to 2024). Status epilepticus is defined as a continuous seizure lasting more than 30 min, or two or more seizures without full recovery of consciousness between any of them. "In kainic acid-induced status epilepticus, the repression of the HCN1 channel was mediated by REST binding, and mild inactivation of REST reduces susceptibility." (PMID 37892159, 2023). "Experimental evidence has shown this subunit is regulated by repressor element 1 (RE1)-silencing transcription factor (REST)-mediated gene silencing as a result of status epilepticus." (PMID 29053743, 2017).
uterine fibroids (4 papers, 2022 to 2026). "We reported previously that the loss of REST protein in uterine leiomyoma allows aberrant expression of GPR10 (PRLHR), a neuronal specific G-protein coupled receptor, leading to cell growth and survival via the PI3K/AKT-mTOR signal transduction pathway." (PMID 39314474, 2024). "Conversely, PRICKLE1 and HB-EGF, two of the REST pathway associated genes with putative roles in the regulation of REST, were down regulated in uterine leiomyomas." (PMID 39314474, 2024). "Diseases including colon cancer, lung cancer, and uterine leiomyomas have also been associated with loss of REST function." (PMID 35177031, 2022). "To elucidate the role of PRICKLE1 in REST stability and to establish a molecular mechanism for their concomitant loss in uterine leiomyomas, we tested whether modulating PRICKLE1 expression levels had an effect on REST protein levels." (PMID 39314474, 2024). "In uterine fibroids, REST represses GPR10 in the normal myometrium, and that the loss of REST in fibroids permits GPR10 expression." (PMID 37892159, 2023). "This mislocalization leads to aberrant expression of REST target genes that contribute to the pathogenesis of uterine fibroids." (PMID 35177031, 2022). "While REST is recognized as a sentinel of cellular identity, its role in uterine fibroids (UF) remains unclear." (PMID 41601477, 2026). "PRICKLE1 regulates REST expression in uterine leiomyomas at protein level." (PMID 39314474, 2024). "While the computational findings provide structural insight into how variants such as Y283C may influence REST behavior, these results are predictive and do not establish direct causality in uterine fibroid pathogenesis." (PMID 41601477, 2026). "The widespread destabilization and loss of REST in the absence of PRICKLE1 expression seen here in uterine leiomyomas is entirely novel, and may provide future therapeutic approaches for restoring REST function." (PMID 39314474, 2024). "We found that uterine leiomyomas expressed significantly lower levels of PRICKLE1, and its expression mirrored that of REST." (PMID 39314474, 2024).
acute myeloid leukemia (3 papers, 2021 to 2022). Acute myeloid leukemia (AML) is a group of neoplasms arising from precursor cells committed to the myeloid cell-line differentiation. "The results showed that the expression of REST was significantly up-regulated in most tumors compared to normal tissues, such as esophageal carcinoma, acute myeloid leukemia (LAML) and testicular germ cell tumors (TGCT) (all p < 0.001)." (PMID 34859007, 2021).
amyotrophic lateral sclerosis (3 papers, 2015 to 2025). Amyotrophic lateral sclerosis (ALS) is a neurodegenerative disease characterized by progressive muscular paralysis reflecting degeneration of motor neurons in the primary motor cortex, corticospinal tracts, brainstem and spinal cord. "Herein, we investigated the role of REST in amyotrophic lateral sclerosis (ALS) pathophysiology and its potential as blood-based predictor of disease prognosis and survival in ALS patients." (PMID 41108075, 2025). "Methylmercury (MeHg) exposure has been related to amyotrophic lateral sclerosis (ALS) pathogenesis and molecular mechanisms of its neurotoxicity has been associated to an overexpression of the Restrictive Element 1 Silencing Transcription factor (REST)." (PMID 34899171, 2021). "It has been previously demonstrated that necroptosis contributes to motor neuron death in amyotrophic lateral sclerosis and that the neurotoxicant PCB-95 activates the necroptotic pathway in cortical neurons via REST up-regulation." (PMID 34899171, 2021).
breast tumors (3 papers, 2010 to 2025). "Using our 24-gene signature, we screened a microarray dataset containing 129 breast tumors for loss of REST function." (PMID 20548947, 2010). "In summary, we show here that REST–less tumors represent a distinct, aggressive subset of breast tumors with a unique disease course." (PMID 20548947, 2010). "We then used the 24-gene signature to classify the breast tumor superseries GSE6532 into REST–less and RESTfl tumors and determined how REST status associated with patient outcome." (PMID 20548947, 2010). "To assay breast tumors for REST function, we developed a 24-gene signature composed of direct targets of the transcriptional repressor." (PMID 20548947, 2010). "We examined gene expression in over 250 samples of tumor and normal tissue in three different publicly available databases and find that breast tumors express REST mRNA at levels at or above those in normal tissue." (PMID 20548947, 2010). "However, the development of a gene signature for loss of REST in vitro allowed for the identification of a class of REST–less breast tumors." (PMID 20548947, 2010). "In this study we demonstrate that REST function is lost in a fraction of breast tumors." (PMID 20548947, 2010). "Immunohistochemical analysis of 182 breast tumors in a tissue microarray confirmed the lack of full-length (functional) REST predicted by the REST4 splicing in 37 (20.3%) tumor samples." (PMID 20548947, 2010).
chronic kidney disease (3 papers, 2023 to 2024). Impairment of the renal function secondary to chronic kidney damage persisting for three or more months. "The previous study found that REST was a crucial inducer of ferroptosis in RIRI and inhibiting REST can alleviate the progression of chronic kidney disease from RIRI." (PMID 38495888, 2024). "Here, we found that REST was upregulated in AKI patients, mice, and RTECs, which was positively associated with the degree of kidney injury, while renal tubule–specific knockout of Rest significantly alleviated AKI and its progression to chronic kidney disease (CKD)." (PMID 37288660, 2023).
COVID-19 (3 papers, 2020 to 2023). A disease caused by infection with severe acute respiratory syndrome coronavirus 2. "Taken together, these data suggest that COVID-19-associated metabolic abnormalities are at least partially dependent on the transcription factor REST and its downstream genes, which include MPO, apelin, and myostatin." (PMID 34916489, 2021). "The REST factor has also increased expression during COVID-19." (PMID 37408184, 2023).
endometrial cancer (3 papers, 2021 to 2025). Primary or metastatic malignant neoplasm involving the endometrium (mucous membrane that lines the endometrial cavity). "Mechanistically, RCOR2 has been implicated in transcriptional repression networks involving REST and HDACs, and may influence endometrial cancer progression by modulating epigenetic landscapes that control proliferation and differentiation pathways." (PMID 40936699, 2025). "Further, we were unable to obtain normal patient tissue specimens adjacent to the tumor in the endometrial cancer samples, which would have helped determine differences in REST expression within a patient depending on tissue morphology." (PMID 39273639, 2024). "We analyzed the expression of REST and MMP24 in 31 cases of endometrial cancer and 16 controls." (PMID 39273639, 2024).
Ewing sarcoma (3 papers, 2014 to 2021). A small round cell tumor that lacks morphologic, immunohistochemical, and electron microscopic evidence of neuroectodermal differentiation. "REST has been shown to control pericyte biology in‐ Ewing's sarcoma, a primitive neuro‐ectodermal tumor that occurs mostly in adolescents." (PMID 33469989, 2021). "Our work implicates WT1 as a global regulator of Ewing sarcoma angiogenesis, and future work will clarify how NPY, REST, and WT1 interact." (PMID 24810959, 2014).
heart failure (3 papers, 2020 to 2024). Inability of the heart to pump blood at an adequate rate to meet tissue metabolic requirements. "GNAO1, which was downregulated by REST, has been reported recently to be a therapeutic target of heart failure." (PMID 39377066, 2024).
kidney cancer (3 papers, 2019 to 2021). Primary or metastatic malignant neoplasm involving the kidney. "In contrast, our findings suggest that the REST expression in kidney cancer patients is associated with patient OS and RFS." (PMID 33834072, 2021). "We used survival analysis to evaluate the effect of the REST expression on the over survival (OS) of kidney cancer patients." (PMID 33834072, 2021). "ARNT, CTCF, POLR2A, RAD21 and REST were downregulated in kidney cancer samples and indicated poor prognosis when lowly expressed, which revealed that ARNT, CTCF, POLR2A, RAD21 and REST tended to be risk factors with lower gene expression." (PMID 31727869, 2019). "However, in the future, the structural network and specific mechanism between REST downregulation and shortened survival time of kidney cancer patients still need to be improved, so as to provide better treatment strategies for KIRC patients." (PMID 33834072, 2021).
malignant glioma (3 papers, 2018 to 2024). A grade III or grade IV glioma arising from the central nervous system. "As expected, EMSA results showed the same pattern as in U87 cells indicating that the binding of REST to the methylated site cg15072976 is commonly affected in malignant gliomas." (PMID 29535343, 2018). "Our findings suggest that REST plays a role specifically in these malignant gliomas." (PMID 38711090, 2024).
melanoma (3 papers, 2023 to 2026). A malignant, usually aggressive tumor composed of atypical, neoplastic melanocytes. "As the REST-CoREST complex specifically regulates repression of differentiation-associated genes during neural development, it is not wholly surprising that this complex would be reactivated to dictate the differentiation/proliferation balance in human melanoma cells." (PMID 38300709, 2024). "This positive correlation with CASP8 in melanocytes and some melanoma tumors is inconsistent with the established role for REST as a transcriptional repressor." (PMID 41542517, 2026). "In melanoma, the decreased REST/RE1 activity leads to aberrant metabotropic glutamate receptor 1 (mGluR1) expression, whose ectopic expression in mouse melanocytes was sufficient to induce melanoma development." (PMID 37892159, 2023).
memory impairment (3 papers, 2015 to 2022). "The plasma REST protein level is decreased in AD dementia patients, which is associated with memory impairment and left temporal lobe atrophy and may have potential value for clinical diagnosis of AD dementia." (PMID 35650520, 2022). "Surprisingly, it is not known whether REST/NRSF-mediated dysregulation of NR1 expression has a causative mechanism in PBDE-209-induced memory impairment and CDRI-08 has capability to revert the effects of PBDE-209 via acting on the same target." (PMID 26413122, 2015).
mental retardation (3 papers, 2011 to 2022). "REST modulates expression of genes encoding fundamental neuronal functions including ion channels, synaptic proteins and neurotransmitter receptors and has been linked to an inherited form of mental retardation." (PMID 21569303, 2011). "This transcription factor regulates the transcriptional repressor REST and is located in a 16q22.1 microdeletion in a family with mental retardation." (PMID 27716060, 2016).
mood disorder (3 papers, 2021 to 2025). A cognitive disorder a disturbance in which the person's mood is hypothesized to be the main underlying feature. "It has been suggested that REST may be involved in the context of mood disorders and the action of antidepressants based on the analysis of its target genes." (PMID 40084057, 2025).
neuroendocrine tumors (3 papers, 2022 to 2025). "Alternative splicing of REST from sREST to REST might be a potential cause of anti-tumor effects by SRRM4 ASO in neuroendocrine tumors SCLC as well as PCa." (PMID 36650528, 2023). "The opposite impact of TF score on the survival of NEL and NBL may attributed to BATF3, GMEB1 and REST, since NFIA and ZNF281 showed uniform influence on the survival of the two neuroendocrine tumors." (PMID 36713370, 2022).
ovarian carcinoma (3 papers, 2021 to 2023). A malignant neoplasm originating from the surface ovarian epithelium. "In ovarian cancer, REST regulates the growth and survival of tumor cells via the regulation of mTOR signaling." (PMID 33834072, 2021). "Previous study found that the down-regulation of NRSF/REST suppresses mTOR signaling in ovarian cancer cells, therefore we asked whether NRSF/REST elevation is related to mTOR activation under HGP exposure." (PMID 35850767, 2022).
virus infection (3 papers, 2021 to 2025). "This review advances the present knowledge of REST in virus infection which will aid in future efforts towards a better understanding of how REST acts in herpesviruses and other viruses for their infections and pathogenesis." (PMID 40006989, 2025). "The role of REST in viral infections is vivid, both in aiding in infection and infection establishment, and in aiding protection against certain viruses." (PMID 40006989, 2025). "There is much scope for unraveling the role of REST in virus infection and such studies still hold importance as REST happens to be a key cellular repressor." (PMID 40006989, 2025). "Even though the role of REST in host cellular gene regulation is well established, its role in the establishment of viral infections and its capability to stabilize and destabilize such viral infections are scarcely studied." (PMID 40006989, 2025). "Here, we summarize all such virus studies involved with REST to gain a better insight into REST biology in virus infections." (PMID 40006989, 2025). "Therefore, the expression of REST upon virus infection was manipulated for further validation." (PMID 34916489, 2021). "Although a highly studied transcriptional regulator, REST in virus infection scenarios has not been well explored." (PMID 40006989, 2025).
brain ischemia (2 papers, 2021 to 2022). Diminished or absent blood supply to the brain caused by obstruction (thrombosis or embolism) of an artery resulting in neurologic damage. "Accordingly, REST has been shown to form a histone deacetylase complex that is a director repressor of SP1 in cerebral ischemia, a TF we identify as varying significantly over space, in the opposite direction of REST37." (PMID 33627658, 2021).